MIR1288 (microRNA 1288)
Synonyms: hsa-mir-1288; MIRN1288
Gene: MicroRNA gene on chromosome 17 (16,282,014 to 16,282,088, forward strand). Ensembl gene ENSG00000221355.
Homologues: Orthologues: macaque MIR1288 (100% identical).